TXNIP (thioredoxin interacting protein)
Diseases named in the same sentence as TXNIP in open-access papers (continued):
Sharing a sentence is not in itself a finding about the gene and the disease.
endothelial dysfunction (continued). "The resulting oxidative stress arises from overexpressed TXNIP, leading to endothelial dysfunction and impaired vasorelaxation." (PMID 33567593, 2021). "As a mechanical explanation, some works show, for example, that TXNIP overexpression induces endothelial dysfunction, vasoregulation disorders, and aortic stiffening via reduced levels of phosphorylated eNOS or NO bioavailability." (PMID 33567593, 2021). "Dunn and co-workers showed that elevated expression of TXNIP protein may trigger endothelial dysfunctions by inhibiting synthesis of vascular endothelial growth factor (VEGF)." (PMID 37462767, 2023). "Taken together, our results suggested that TXNIP is a key component involved in mediating shear stress-induced inflammation, energy homeostasis, and glucose utilization, and that TXNIP may serve as a potentially novel endothelial dysfunction regulator." (PMID 36465470, 2022). "In addition, metformin and many other compounds were used to lower aortic TXNIP levels in vivo or endothelial levels in vitro to block NLRP3 inflammasome activation and protect from endothelial dysfunction and cardiovascular risk factors." (PMID 36252682, 2022). "Indeed, a recent report showed that high glucose-treated HUVEC downregulate lnc-SNHG15, which reduces TXNIP expression by enhancing its ubiquitination, thus mitigating high glucose-induced endothelial dysfunction." (PMID 34944690, 2021). "Therapies targeting endothelial TXNIP could thus delay endothelial dysfunction and the onset of cardiovascular complications induced by aging and its comorbidities." (PMID 33567593, 2021). "Therefore, therapies that target endothelial TXNIP may postpone the development of cardiovascular complications brought on by aging and its comorbidities, as well as endothelial dysfunction." (PMID 36830671, 2023). "In addition, the team found that knockdown of TXNIP could alleviate high glucose-mediated endothelial dysfunction." (PMID 36389728, 2022). "Indeed, endothelial dysfunction induced by high levels of TXNIP may have profound effects on the vasculature, a characteristic feature of metabolic disorders." (PMID 33567593, 2021). "Routine exercise alleviates endothelial dysfunction in atherosclerotic coronary arterioles in an eNOS, UCP2, and ER stress signaling specific manner, and resulting in reduced TXNIP/NLRP3 inflammasome activity and oxidative stress." (PMID 34326395, 2021). "For instance, it was proposed that TMAO-induced inflammation may activate the inflammasome ROS-thioredoxin interacting protein (TXNIP)-NLRP3, which in turn could lead to endothelial dysfunction in the endothelial cells of umbilical vein of humans." (PMID 40100371, 2025). "Similarly, aerobic exercise also can inhibit the thioredoxin interacting protein (TXNIP)/NLRP3 inflammasome pathway and alleviate endothelial dysfunction in atherosclerotic coronary arterioles." (PMID 38681198, 2024). "Considering both endothelial dysfunction and GLUT1 dysregulation are common in ischemic stroke and TXNIP can influence both changes, it can be assumed that TXNIP may be a potential target to regulate GLUT1 in ischemic ECs." (PMID 38747733, 2024). "Further confirmation of disturbed flow inducing endothelial dysfunction through regulating TXNIP expression was queried through treating the cells with either TXNIP-siRNA or negative control siRNA (NC-siRNA)." (PMID 36465470, 2022). "However, the direct effects of TXNIP on NO regulation in disturbed flow-induced endothelial dysfunction were not investigated." (PMID 36465470, 2022). "However, the role of TXNIP in endothelial dysfunction is not well addressed." (PMID 36465470, 2022).
melanoma (29 papers, 2013 to 2026). A malignant, usually aggressive tumor composed of atypical, neoplastic melanocytes. "BRAFi, which has been approved to treat advanced melanoma and proved to show strong clinical benefit in BRAFv600 melanoma, can also induce TXNIP expression through regulating the association between MondoA and TXNIP promoter." (PMID 37794178, 2023). "In contrast, reduced TXNIP expression associates with advanced melanoma and with disease progression in patients." (PMID 33846376, 2021). "TXNIP was first identified as a metastasis suppressor due to the low expression of TXNIP in metastatic melanoma cells caused by Chr6 deletion." (PMID 26196741, 2015). "Thus, it was suggested that reduced TXNIP expression is associated with melanoma progression and exerts a pro-tumorigenic effect." (PMID 36834531, 2023). "Our study reveals that a progressive decrease in TXNIP expression is associated with the progression of melanoma towards a metastatic phenotype, whereas high TXNIP expression level associates with tumor regression (RECIST) and with decreased proliferation in patients on MAP kinase targeted therapy." (PMID 33846376, 2021). "Together, our findings revealed that GPR161 promotes melanoma malignancy by linking STAT3 activation to TXNIP suppression and metabolic enhancement." (PMID 41834581, 2026). "TXNIP has been proposed as a tumor suppressor gene in several cancers, including breast, melanoma, and lung." (PMID 41213907, 2025). "Downregulation of TRX inhibitor-thioredoxin-interacting protein (TXNIP) promotes melanoma progression and lung metastases, while TRX expression and secretion to TME generate immunotolerance." (PMID 39519202, 2024). "In melanoma, miR-224/452-mediated downregulation of TXNIP is essential for E2F1-induced EMT and invasion." (PMID 38890620, 2024). "Activation of PPARγ led to reduced expression of thioredoxin-interacting protein (TXNIP) in human melanoma A375 cells." (PMID 36834531, 2023). "Mir-152-5p promoted metastasis and invasive features of BRAFi-resistant melanoma by blocking metastasis suppressor gene TXNIP." (PMID 36982460, 2023). "Overexpression of TXNIP turned out to be a major inhibiting factor for cell migration and invasion in BRAFi-resistant melanoma cells." (PMID 36982460, 2023). "Overexpression of TRX blocked hydrogen peroxide-induced TEM, demonstrating a cooperative role of TXNIP in melanoma progression that can be reversed by Trx." (PMID 35326089, 2022). "The negative regulator of TRX, thioredoxin interacting protein (TXNIP), has been shown to have a reduced expression from benign nevi to primary melanoma and a further reduced expression in metastatic melanoma." (PMID 35326683, 2022). "TXNIP is downregulated after BRAFi treatment in melanoma, and overexpression of TXNIP in BRAFi resistant cells decreased migration and invasion." (PMID 35326089, 2022). "TXNIP depletion in human melanoma cells altered the expression of integrin beta-3 and the localization of the integrin alpha-v/beta-3 dimer at their surface." (PMID 33846376, 2021). "To shed light onto the potential roles of TXNIP in human melanoma cells, we performed an RNA-seq on A375 cells transiently transfected with TXNIP versus control siRNA." (PMID 33846376, 2021). "We next examined the functional impact of TXNIP-dependent regulation of genes involved in melanoma cell adhesion and migration—two critical processes for metastasis formation." (PMID 33846376, 2021). "TXNIP-dependent regulation of human melanoma cell adhesion was assessed using trypsin resistance assays as well as conventional adhesion assays." (PMID 33846376, 2021). "We next assessed the impact of TXNIP downregulation in melanoma cells in vivo using only A375 metastatic cells as a model in order to limit animal use." (PMID 33846376, 2021).
melanoma (continued). "Using bioinformatics analyses of public data, cell culture and in vivo models, we identify TXNIP as a PPARγ-regulated gene, the downregulation of which during melanoma progression likely contributes to malignant cell seeding to distant organs." (PMID 33846376, 2021). "We next addressed TXNIP role in melanoma cell seeding to distant organs by quantifying the ability of fluorescently-labelled TXNIP-deficient A375 cells to establish lung tumors following injection into the tail vein of immunocompromised mice." (PMID 33846376, 2021). "With this approach, we found that TXNIP expression was downregulated by PPARγ activation in A375 metastatic melanoma cells (absolute fold change −1.36; False discovery rate 0.031;7)." (PMID 33846376, 2021). "We next mimicked the decreased TXNIP expression that seemingly occurs in the course of melanoma progression." (PMID 33846376, 2021). "Along the same line, increased expression of TXNIP in On-treatment specimens was associated with decreased expression of the proliferation marker PCNA and lower proportion of Ki67-positive melanoma cells in 10 out of the 12 patient samples analyzed." (PMID 33846376, 2021). "This suggests context-dependent consequences in modulating TXNIP activity in melanoma, the characterization of which requires further investigation." (PMID 33846376, 2021). "The relative protein expression levels of TXNIP were downregulated in all three melanoma cell lines, and the mRNAs expression levels of TXNIP were downregulated in A375 and MV3 cell lines, compared with NHEM." (PMID 34447410, 2021). "This study establishes TXNIP as a PPARγ-regulated gene in melanoma cells, thereby suggesting a link between these two proteins both involved in the regulation of cancer and of energy metabolism." (PMID 33846376, 2021). "miRNA-224-5p can be regulated by E2F1 to drive EMT through TXNIP downregulation in melanoma, and it can inhibit uveal melanoma cell proliferation, migration, and invasion by targeting PIK3R3/AKT3." (PMID 32993558, 2020). "TXNIP-transfected melanoma cells resulted in fewer metastases in both a nude mouse flank tumor model and IV tail injection metastasis model relative to vector controls." (PMID 24645981, 2014). "In melanoma, TXNIP expression is enriched in memory T cells." (PMID 37794178, 2023). "A375 melanoma tumour development and metastasis can be dysregulated in opposite ways as a result of GLO1 deletion, as was shown by the observation of an enhanced growth rate of GLO1 KO tumours in a SCID mouse melanoma xenograft model, together with TXNIP overexpression and metabolic reprogramming." (PMID 37238995, 2023). "A striking example in which the miR-224/452 cluster simultaneously controls cellular metabolism was found in malignant melanomas, in which both miRs targeted thioredoxin interacting protein (TXNIP), a key transcription factor involved in redox regulation and tumor suppression." (PMID 34342596, 2021). "Our study suggests that in melanoma, reactivation of TXNIP expression may be of interest to reduce malignant cell invasive capacities." (PMID 33846376, 2021). "The present study aims to elucidate TXNIP functions in human melanoma." (PMID 33846376, 2021). "We thus sought to assess what contribution could TXNIP make to the roles played by PPARγ and its agonists in melanoma cells." (PMID 33846376, 2021). "Moreover, TXNIP depletion affected human melanoma cell motility and improved their capacity to colonize mouse lungs in an in vivo assay." (PMID 33846376, 2021). "Here we reveal that PPARγ activation reduces the expression of TXNIP in human melanoma cells." (PMID 33846376, 2021).
melanoma (continued). "In agreement with an active role of TXNIP in controlling melanoma cell adhesion, conventional adhesion assays revealed enhanced adhesion of A375-shTXNIP cells on plates coated with fibronectin, while C8161-shTXNIP cells exhibited decreased adhesion on the same substrate." (PMID 33846376, 2021). "Moreover, several of the most deregulated KEGG pathways were related to cell adhesion, overall suggesting a potential role of TXNIP in melanoma cell dissemination." (PMID 33846376, 2021). "The contribution of TXNIP to the progression of melanoma is unknown, despite evidence of TXNIP-dependent regulation of proliferation, ROS levels and intravasation in mouse or human melanoma cells." (PMID 33846376, 2021). "Furthermore, overexpression of TXNIP in melanoma cells results in the inhibition of metastasis, suggesting that TXNIP can suppress metastasis." (PMID 24098117, 2013). "We show that high TXNIP expression levels associate with benign melanocytic lesions, with tumor regression in patients on MAP kinase targeted therapy, with decreased proliferation in patients’ melanoma biopsies, and with cell cycle arrest in human melanoma cell lines." (PMID 33846376, 2021). "In addition, the expression of AFF1, PIM1, PTPN13 and TXNIP was downregulated in UV-irradiated FM SFs with a R87P-CDKN2A mutation, and the expression of these genes was also found to be downregulated in melanoma tissue." (PMID 23371019, 2013). "In TNBC, upregulated MYC inhibits the MondoA-dependent activation of TXNIP to stimulate glycolysis, while in BRAF-mutant melanoma, the MYC-induced downregulation of the MondoA-TXNIP axis leads to vemurafenib resistance." (PMID 37443779, 2023). "According to our analysis, 66% of the isoforms presented differential expression on melanoma progression: NOS2, SOD1, NOX4, PRX3, PXDN and GPX1 are increased during melanoma progression, while CAT, GPX3, TXNIP, and PRX2 are decreased." (PMID 35326089, 2022). "Here we identify the Thioredoxin-interacting protein (TXNIP) as a gene, which expression is regulated by PPARγ in melanoma cells." (PMID 33846376, 2021). "Besides, iNOS, SOD1, NOX4, PRX3, PXDN and GPX1 are generally increased during melanoma progression, while CAT, GPX3, TXNIP and PRX2 are decreased." (PMID 35326089, 2022). "In accordance with this potential limitation, Goldberg and colleagues failed to see slowed in vitro growth of melanoma cells transfected with TXNIP though when injected in an orthotopic flank model in nude mice, slowed tumor growth/development was observed." (PMID 24645981, 2014). "Nevertheless, we were able to obtain reproducible up‐regulation of genes including EGR1, TXNIP, AXL, CYR61, LIMS2 and TNFRSF12A in MDA‐MB‐435s and MV3 melanoma cell lines and significant increase in protein levels as well, suggesting potential implication in other melanoma cells." (PMID 31044520, 2019). "Finally, downregulation of TXNIP expression levels by RGZ was not specific to the A375 metastatic cells, as it was also observed in the human melanoma cell lines WM35 (radial-growth phase), WM115 (vertical-growth phase), SK-MEL-28 (metastatic) and WM793 (metastatic) human melanoma cells." (PMID 33846376, 2021).
Obesity (29 papers, 2013 to 2024). Accumulation of substantial excess body fat. "The depletion of fat mass and obesity-associated protein can enhance the mRNA stability and expression of thioredoxin-interacting protein (TXNIP), thereby enhancing ROS production and NLRP3 inflammasome activation." (PMID 38249297, 2023). "Conversely, TXNIP overexpression worsened obesity‐associated cardiomyopathy." (PMID 39604027, 2024). "TXNIP is the most replicated DNA methylation marker associated with T2D, indeed alterations at TXNIP may also occur in response to obesity or hyperlipidaemia prior to the onset of T2D." (PMID 38288471, 2023). "However, the extent to which the anti-obesity effects of SalA exerted through regulating TXNIP-mediated signaling implicated in hepatic lipogenesis account for the overall improvement of NAFLD in HFD-fed rats remains to be further explored." (PMID 27345365, 2016). "However, this is the first report in which it was found that T allele is a protective factor against obesity and we suggest that TXNIP expression or function would be affected allowing TXN to exert its antioxidant action." (PMID 27274779, 2016). "Considering these findings together with our results, we speculate that SalA might play a role in diet-induced obesity, and this effect may be associated with regulating the TXNIP-ChREBP pathway to a certain extent." (PMID 27345365, 2016). "Cardiomyocyte TXNIP overexpression aggravated obesity‐induced cardiac dysfunction, lipid accumulation, and cardiac remodeling." (PMID 39604027, 2024). "Our results suggest that mitochondrial ROS‐mediated TXNIP/NLRP3 inflammasome activation in cardiomyocytes plays a critical role in the pathogenesis of obesity cardiomyopathy." (PMID 39604027, 2024). "The current study confirmed that mitochondrial ROS‐mediated TXNIP/NLRP3 inflammasome activation in cardiomyocytes plays a critical role in the pathogenesis of obesity cardiomyopathy." (PMID 39604027, 2024). "TXNIP gene-deletion mice have been shown in general to be protected from the vascular consequences of high-fat/obesity or high-sugar diets compared to wild-type mice." (PMID 33302545, 2020). "A direct link between metabolic activity and TXNIP was demonstrated in mice with the expression of TXNIP in medial hypothalamic neurons, which increased under conditions of nutrient excess and obesity." (PMID 33302545, 2020). "TXNIP expression is sharply regulated in many tissues by physiological conditions, which limits the glucose metabolism such as fasting and obesity-prediabetic condition." (PMID 32824669, 2020). "This study shows that the rs7211 polymorphism in the TXNIP gene and the rs2071749 of the HMOX1 gene are associated with obesity in Mexican mestizo people." (PMID 27274779, 2016). "Molecular pathway analysis of LRRK2 reveals direct links between LRRK2 and the thioredoxin system, which interacts with PRDX3, TXNIP and TXNRD1, proteins that are associated with nutrient sensing, adiposity and human obesity." (PMID 23799078, 2013). "TXNIP expression in β-cells is elevated in diabetic rodent models with and without obesity, and TXNIP deficiency protects β-cells from death." (PMID 36139067, 2022). "It is also important to note the effect of TXNRD in obesity and adipogenesis may be at least partially mediated through modulation of thioredoxin and thioredoxin interacting protein (TXNIP) levels, being involved in redox regulation of adipogenesis." (PMID 32344656, 2020). "Here, we found that some DMR genes are obesity genes or related to the former which have been studied by genomic and genome-wide association study (GWAS) methods, for example, FTO, PCSK5, PCSK6, NTRK2, ABCC4, TXNIP and RPS6KA2." (PMID 31637123, 2019). "However, whether TXNIP/NLRP3 inflammasome activation contributes to the development of obesity cardiomyopathy remains unknown." (PMID 39604027, 2024). "Notably, TXNIP overexpression exacerbated obesity‐induced cardiac hypertrophy." (PMID 39604027, 2024).
Obesity (continued). "Thioredoxin-interacting protein (TXNIP) has been identified as a key factor in beta-cell biology and glucose homeostasis that is correlated with obesity." (PMID 36733403, 2023). "In a rat model of obesity, high-fat diet (HFD)-fed rats, both wild-type and spontaneously hypertensive rats, had evidence of abnormal capillary formation and degeneration along with the enhanced expression of TXNIP, NFκB, and inflammatory cytokines IL-1β and TNFα." (PMID 33302545, 2020). "Interestingly, verapamil was able to mimic the anti-diabetic effects of genetic TXNIP deletion observed in mouse models of T1D and T2D again using STZ-induced and obesity-induced diabetic mice treated with or without oral verapamil." (PMID 39429740, 2024). "Our results showing that TXNIP deletion preserves insulin sensitivity without affecting weight gain or obesity lend further support to prior studies using TKO in HFD diet-induced and genetic obesity models." (PMID 28661427, 2017).